TLR2 (toll like receptor 2)
Diseases named in the same sentence as TLR2 in open-access papers (continued):
Sharing a sentence is not in itself a finding about the gene and the disease.
Sepsis (continued). "Interestingly, the MFI for TLR2 in both CD56bright and CD56dim was significantly increased for sepsis patients compared to healthy volunteers." (PMID 23098236, 2012). "Similarly, the MFI of intracellular TLR2 in CD56bright and CD56dim subsets was significantly increased in sepsis patients compared to healthy controls." (PMID 23098236, 2012). "To test this hypothesis, we conducted a case control study using a tag SNP approach to investigate the association of variants in TLR2, TLR4, TLR9, MyD88, and TOLLIP with susceptibility to sepsis in the Chinese Han population." (PMID 21219635, 2011). "Of further interest, both Ppargc1 genes are up-regulated in sepsis through an unknown cascade involving the TLR2 and TLR4 signaling pathways." (PMID 21966468, 2011). "Moreover, evidence in the literature on the role of mast cells in innate immunity and the results presented here regarding cross-tolerance between TLR4 and TLR2 highlight the relevance of these findings with respect to sepsis." (PMID 20707930, 2010). "We examined the expression of genes of mitochondrial biogenesis program in this sepsis model in the livers of WT, TLR2−/−, and TLR4−/− mice in order to compare the wild-type response to the effects of specific innate immune receptor deficiencies on mitochondrial biogenesis." (PMID 20657826, 2010). "We suggest that CD14 and TLR2 are a key factor in monocyte hyporesponsibility during severe sepsis." (PMID 19371402, 2009). "The central role of TLR2 and TLR4 in microbial responses suggests that they may be implicated in the pathophysiology and the outcome of human sepsis." (PMID 19371402, 2009). "TLR2 is known to be activated by structures on Gram-positive bacteria such as lipoproteins and peptidoglycan, but the receptor has also been described to recognize a soluble factor from group B streptococci isolated from newborn infants with sepsis." (PMID 16504163, 2006). "Moreover, studies have shown that TLR4 knockout mice were resistant to Gram-negative bacteria-induced septic shock 11 whereas TLR2-deficient mice had increased survival rates compared with the wild-type ones in a polymicrobial sepsis model." (PMID 40963927, 2025). "Notably, TLR signaling pathway analysis revealed that TLR2 and/or TLR4 deficiency substantially attenuated IGFBP6 expression in PLF, pulmonary tissue, macrophages, and epithelial cells during sepsis, establishing TLR2/4-mediated regulation of IGFBP6 production." (PMID 40892465, 2025). "Interestingly, the difference in mortality related to light or dark phase induction of CLP was lost in TLR2-/- female mice, indicating that TLR2 may play a role in circadian-dependent mortality outcomes in murine models of sepsis." (PMID 39968295, 2025). "Moreover, TLR2 and TLR4 polymorphisms are associated with a higher risk of staphylococcal or gram-negative infections, further underscoring the involvement of TLRs in sepsis." (PMID 38835761, 2024). "Combined with the results of in vitro studies on macrophages, the potential mechanism by which rEgAgB ameliorates sepsis-induced hyperinflammatory response may be to shift the M1-like to M2-like phenotype of macrophages through inhibiting TLR2 and MyD88 pathways." (PMID 39548530, 2024). "Additionally, TLR2 had a substantial immunosuppressive effect on the spleen due to sepsis." (PMID 38685971, 2024). "Moreover, because TLR2 senses the S. aureus lipoprotein and plays a potent role in S. aureus infections, it may contribute to sepsis pathogenesis in the context of aging." (PMID 36808423, 2023). "Thus, TLR2 plays an important role in exacerbation of the inflammatory activity in sepsis." (PMID 38094127, 2023). "Consequently, many studies have been conducted all over the world to reveal the prevalence of these SNPs and their impact on infection and sepsis susceptibility, but a varied pattern of prevalence was found for both TLR4 and TLR2 SNPs among different populations." (PMID 36142893, 2022).
Sepsis (continued). "Furthermore, the expression of TLR-2,4 at early stages of sepsis correlates with mortality." (PMID 36142743, 2022). "However, activation of TLR2 signaling is crucial for improving the immune function during sepsis." (PMID 32197507, 2020). "We found that AML patients who have TLR2 Arg753Gln: AG genotypes and A allele; TLR4 Asp299Gly: CT genotype and C allele; TLR4 Thr399Ile AG genotype and A allele showed significant higher association to sepsis and pneumonia as compared to other genotypes and alleles." (PMID 33247673, 2020). "Further supporting this hypothesis, it is well known that TLR2 and TLR4 are crucial in host defense against several bacterial pathogens that, like B. microti, cause sepsis like Staphylococcus aureus, Streptococcus pneumoniae, Klebsiella pneumoniae, Haemophillus influenza and Acinetobacter baumanii." (PMID 28119856, 2016). "Further research should be focused on whether MFHAS1 has the same effect on TLR2, using other ligands like bacterial lipopeptides, and animal experiments should be performed to further verify the effect of MFHAS1 on the TLR2 signaling pathway, and its effect on inflammation and sepsis." (PMID 26599367, 2015). "Seventh, we could discuss only the association between the TLR2 Arg753Gln polymorphism and sepsis risk in two genetic models for the lack of a mutant homozygote." (PMID 26616674, 2015). "Unlike TLR4and TLR3, TLR2 is associated with deleterious systemic inflammation, cardiac dysfunction, acute kidney injury (a common entity in critically ill patients) and is mostly triggered by severe sepsis." (PMID 26599367, 2015). "Therefore, our data suggest that neutrophil associated uPAR could be a potential target for treating acute inflammation, sepsis, and organ injury related to severe bacterial and other microbial infections in which TLR2 engagement plays a major role." (PMID 21998707, 2011). "Therefore, neutrophil associated uPAR could be a potential target for treating acute inflammation, sepsis, and organ injury related to severe bacterial and other microbial infections in which TLR2 engagement plays a major role." (PMID 21998707, 2011). "Its interactions with TLR2, TLR4, and RAGE drive inflammation, contributing to the cytokine storm in sepsis and promoting multiorgan damage." (PMID 40779122, 2025). "TLR2 and TLR4 are the most studied TLRs in sepsis, and selective targeting of these receptors using monoclonal antibodies has shown promise." (PMID 40386784, 2025). "To confirm this, we analyzed the GEO database of pediatric and adult septic patient samples for the correlation of TLR2 and TLR4 expressions with the disease development and progression in sepsis." (PMID 40963927, 2025). "The primary signaling pathway activated by TLR2 and TLR4 in sepsis is the nuclear factor-kappa B (NF-κB) pathway." (PMID 40386784, 2025). "Our previous research demonstrated that the Tlr2/NF‐κB signalling axis upregulates CCL2 in proximal tubular epithelial cells, significantly promoting inflammation and AKI during sepsis." (PMID 40717237, 2025). "The humanized anti-TLR2 monoclonal antibody OPN-305 has exhibited favorable safety and efficacy profiles in clinical trials for sepsis and ischemia–reperfusion injury." (PMID 40137296, 2025). "Recognition of bacterial PAMPs by TLRs (TLR2, TLR4, TLR5, TLR9) activates NF-κB via MyD88-dependent and -independent pathways, leading to pro-inflammatory cytokine production and potentially sepsis." (PMID 40386784, 2025). "Toll-like receptor 2 (TLR2) and TLR4 signaling pathways are pivotal to the pathogenesis of sepsis from the clinical data analysis." (PMID 40963927, 2025). "TLR2 and TLR4 play a significant role in the recognition of these pathogens and the subsequent release of inflammatory cytokines during sepsis." (PMID 38835761, 2024). "The levels of TLR2 and MyD88 were measured in these tissues to determine the involvement of TLR-2/MyD88 in the sepsis-induced inflammatory signaling pathway." (PMID 39548530, 2024).
Sepsis (continued). "In a mouse model of sepsis, this substance inhibited the production of TNF-α and IL-6 in peritoneal macrophages in a dose-dependent manner by inhibiting the expression of Toll-like receptor 2 (TLR2) and suppressing the activation of NF-κB." (PMID 39057789, 2024). "In particular, the upregulation of MPO, MMP9, TLR2, and LCN2 in the lungs of sepsis-induced ARDS mice suggests their crucial role in developing lung injury in COVID-19 and sepsis." (PMID 37822934, 2023). "Our results showed that genes such as IFN-γ, TNF-α, IL-6, MIP-2, IL-10, KC (CXCL1), CCL-2, MPO, MMP9, TLR2, and LCN2 were significantly upregulated in the lungs of sepsis-induced ARDS mice compared to control mice." (PMID 37822934, 2023). "In recent years, TLR2 and TLR4, which are found on immune cells such as monocytes, endothelial cells, or platelets, have gained attention in the context of human sepsis." (PMID 37569837, 2023). "Elevated levels of TLR2 in multiple organs of old mice augment the expression of cardiodepressant cytokines TNF-α, IL-1β, IL-6 and MCP-1 during sepsis, leading to greater cardiac dysfunction and high mortality." (PMID 38094127, 2023). "Here, we show that, early during sepsis, bystander-activated CD8+ T cells accumulate in the BM, are impaired in IFN-γ synthesis due to TLR2 signaling, and control the number and the function of differentiating DCs." (PMID 36148245, 2022). "Reinforcing this observation, genes involved in the MAPK, mTOR, TLR2/MyD88 and JAK/STAT pathway are also up-regulated in the LPS group, as recently described in sepsis patients, confirming the pertinence of such approaches." (PMID 35742875, 2022). "Differential analysis of SIRT1, TLR2, and HSP90AA1 in the sepsis liver injury-control group (SLi-C), p-value were all <0.05, and differential expression." (PMID 36406124, 2022). "Adoptive transfer experiments and in vitro studies with purified T cells revealed that Toll-like receptor 2 (TLR2) signaling in CD8+ T cells suppressed their capacity to secrete IFN-γ and was sufficient to change the transcriptome of the BM during sepsis." (PMID 36148245, 2022). "The high expression of some proteins, such as TLR2, TLR3, and TLR4, have been demonstrated to play a crucial role in sepsis-induced acute injury of the lungs, kidneys, and intestine." (PMID 34938184, 2021). "Another study revealed that PJA2 contributed to MFHAS1 ubiquitylation, positively regulating TLR2-mediated JNK/p38 pathway, which stimulated M1 macrophage polarization as well as M2 to M1 macrophage transformation in sepsis." (PMID 34372882, 2021). "They showed that SAA1 via the TLR2/TLR4/NF-κB signaling pathway mediates C2C12 myotube atrophy in vitro and sepsis-induced muscle atrophy in mice in vivo." (PMID 34572540, 2021). "Further, experiments with myocyte-specific deletions of TLR2 and or TLR4 are needed to state that these receptors mediate sepsis-induced muscle atrophy in vivo." (PMID 34572540, 2021). "Recent work has described the activation of both TLR2 (recognition of bacterial cell wall components) and TLR4 (recognition of lipopolysaccharide) as a consequence of bacterial mediated sepsis leading to ARDS." (PMID 33471802, 2021). "In this study we have presented results demonstrating that Ts-AES strongly alleviate excessive inflammation via stimulating Tregs response and inhibiting the HMGB1/TLR2/MyD88 signal pathway, and protect mice from ALI induced by sepsis." (PMID 33842398, 2021). "Consistently, two TLR2 agonists, named MALP-2 and Pam3Cys, provoke the cytokine and chemokine secretion and prevent the sepsis-induced early depletion of splenic DC." (PMID 32197507, 2020). "In the case of TLR2, interaction with lipoproteins from GBS is an important outcome for sepsis development." (PMID 31963234, 2020). "Separately, it was reported that the expression levels of positive activated molecule NK62D, TLR-2/4/9, and CD69 on NK cells and plasma IFN-γ in sepsis patients were significantly higher than those in healthy controls." (PMID 33076951, 2020).
Sepsis (continued). "During sepsis, SAA1 is increased in muscle and directly acts on myocytes via the TLR2/TLR4/NF‐κB p65 axis." (PMID 31441598, 2020). "In term neonates with late-onset sepsis, TLR4 expression was increased in infants with positive blood cultures and TLR2 expression was raised in those with clinical sepsis." (PMID 31611734, 2019). "Many previous studies have demonstrated the role of TLR2 and TLR4 inhibition in the pathogenesis of sepsis." (PMID 30814582, 2019). "Previous studies have shown that baseline monocyte expression of TLR2 and TLR4 in patients with sepsis in intensive care is significantly up-regulated compared with healthy controls." (PMID 31612119, 2019). "Analyses of publicly available datasets showed that TLR2 mRNA was induced in whole blood samples from pediatric patients suffering from SIRS or sepsis." (PMID 31396208, 2019). "In general these studies have shown that TLR2 and TLR4 contribute to high mortality and multiorgan dysfunction in animal models of polymicrobial sepsis." (PMID 30364002, 2018). "Evidence came from the observation that the expression of both TLR2 and TLR4 was up-regulated during their ligand stimulation in monocytes from healthy subjects, as well as in PBMC from sepsis patients." (PMID 28769820, 2017). "Circulating extracellular histones in plasma have been detected in septic patients, and it interacts with TLR2 and TLR4 on a variety of different cell types and contributes to endothelial dysfunction, organ failure, and death in experimental sepsis." (PMID 28970829, 2017). "Therapeutic effects of treatment with anti-TLR2 and anti-TLR4 monoclonal antibodies have been investigated in a mouse study against polymicrobial sepsis." (PMID 29096690, 2017). "The expression levels of cell surface TLR2 and TLR4 on PMN is usually up-regulated upon stimulation by bacterial products, LPS or lipopeptides, as well as during sepsis." (PMID 27802348, 2016). "Whole blood from sepsis survivors and controls was either incubated with the T cell activator α-CD3/28, or the monocyte/macrophage-activators LPS (via TLR4) or zymosan (via TLR2/Dectin-1)." (PMID 27056672, 2016). "This study aimed to examine the relationship of MFHAS1 and sepsis, and the effect of MFHAS1 on the TLR2 signaling pathway." (PMID 26599367, 2015). "When DCs were stimulated with TLR2 agonist (Pam3Cys) or TLR4 agonist (LPS) or TLR9 agonist (CpG-DNA), mRNA levels of both Il12 p40 and Il12p35 from sepsis splenic DCs were significantly lower than that from sham splenic DCs." (PMID 25821827, 2015). "Protective effects were observed even when the administration of either anti-TLR2 or anti-TLR4 alone was delayed (i.e., 3 h after sepsis induction)." (PMID 26147469, 2015). "Whereas some consider TLR4 signaling to be prosurvival for DCs, others have reported proapoptotic roles of TLR2 and TLR4 in polymicrobial sepsis." (PMID 26440998, 2015). "We have previously demonstrated that TLR2, TLR4 and TLR9 play a deleterious role in polymicrobial sepsis." (PMID 25084278, 2014). "Functionally, the ENV TMD inhibits TLR2 signaling in response to LTA and inhibits secretion of pro-inflammatory cytokines both in vitro and in an animal model of LTA/GLN sepsis." (PMID 25121610, 2014). "The aim of our study was to analyze the expression of TLR2, TLR4 and TLR9 in patients with symptoms of sepsis after intensive induction chemotherapy for AML." (PMID 25412934, 2014). "In sepsis, E. coli PAL is a potent TLR2 agonist, which contributes to inflammation, cardiac dysfunction, endothelial activation, coagulopathy, and vascular leakage." (PMID 25287420, 2014). "Herein, we will review the most popular agonist (TLR3, TLR5, TLR7, TLR8, TLR9) and antagonist (TLR2, TLR3, TLR4, TLR9) agents used in pre-clinical and clinical models of acute and chronic infections, including sepsis." (PMID 24302927, 2013). "It has been reported that TLR2 and TLR4 are regulated in the lung, liver, and spleen in mice suffering from polymicrobial sepsis." (PMID 23935245, 2013).
Sepsis (continued). "C57BL/6 TLR2−/−, TLR4−/− and MyD88−/− male mice were subjected to sepsis by cecal ligation and puncture (CLP)." (PMID 22655058, 2012). "In contrast, a strong intracellular expression of TLR2 was detected after cell permeabilization in both subsets in healthy donors, as well as in SIRS and sepsis patients." (PMID 23098236, 2012). "Intracellular levels of TLR2 and TLR4, in both CD56bright and CD56dim NK cell subsets from sepsis patients, were increased compared to healthy subjects." (PMID 23098236, 2012). "Initially, we observed that there was an up-regulation of TLR2, TLR4 and MyD88 in the WT mice that were subjected to sepsis." (PMID 22655058, 2012). "For the first time, we explored TLR2, TLR4 and TLR9 expression on and in human blood NK cells during sepsis." (PMID 23098236, 2012). "• Intracellular expression of TLR2 and TLR4 in both CD56Dim and CD56Bright NK cell subsets is enhanced during sepsis." (PMID 23098236, 2012). "Among them, TLR2, TLR4, and TLR9 have been established to play a key role in the mediation of systemic responses to invading pathogens during sepsis." (PMID 21219635, 2011). "As shown by other investigators before, CD14, TLR2 and TLR4 protein expression on monocytes is elevated during sepsis." (PMID 19371402, 2009). "Protein expression of CD14, TLR2 and TLR4 on blood monocytes was examined using flow cytometry from 29 patients with sepsis and 14 healthy controls." (PMID 19371402, 2009). "The monocyte expression of TLR2, TLR4 and CD14 was at all timepoints [admission (t0), day 1 (t1) day 3 (t2) and day 7 (t3)] significantly higher in patients with sepsis compared to the monocyte expression in healthy controls." (PMID 19371402, 2009). "We found an increased expression of CD14, TLR2 and TLR4 in patients with sepsis compared to controls (p < 0.01)." (PMID 19371402, 2009). "We therefore compared the TLR2, TLR 4 and CD14 expression on blood monocytes of patients with sepsis and healthy controls." (PMID 19371402, 2009). "In the present study, we evaluated the expression of TLR2, TLR4, CD11b, CD11c and CD66b on the cell surface of neutrophils in patients with sepsis, severe sepsis and septic shock, and compared the findings with those from healthy volunteers." (PMID 18302745, 2008). "These ex vivo effects were largely dependent on Toll-like receptor 2 (TLR2), and sleep interruption no longer exacerbated sepsis in TLR2 knockout mice." (PMID 42257268, 2026). "Thus, the activation of both TLR2 and TLR4 is expected to play a critical role in the pathogenesis of sepsis." (PMID 40963927, 2025). "These multiple lines of evidence indicate that simultaneous inhibition of TLR2 and TLR4 activation may serve as a promising therapeutic strategy for controlling overwhelming inflammation in sepsis." (PMID 40963927, 2025). "The pharmacological blockade of TLR2 and TLR4 signaling by antagonistic antibodies or small molecule inhibitors (e.g., TAK-242 for TLR4) successfully reduced the disease severity in bacteria-induced sepsis mouse models 13-15." (PMID 40963927, 2025). "Among the ten identified human Toll-like receptors (TLRs), TLR4 and TLR2 are the two major contributors to the pathogenesis of sepsis 9, 10, as they sense Gram-negative and Gram-positive bacteria, respectively, to launch inflammatory reactions." (PMID 40963927, 2025). "It has previously been demonstrated that TLRs such as TLR-2, TLR-3, TLR-4, and TLR-7 are highly expressed in the lung tissues of septic mice, therefore suggesting a potential role in the pathogenesis of ARDS during sepsis." (PMID 40076895, 2025). "The identification of the tubular TLR2/NF-κB/CCL2 signaling pathway and the inhibition of the TLR4/NF-κB pathway represent promising strategies for addressing purulent AKI and related renal injuries in sepsis." (PMID 40386784, 2025).